OR52E1 (olfactory receptor family 52 subfamily E member 1 (gene/pseudogene))
Description:
Odorant receptor.
Synonyms: OR52E1P
Gene: Protein-coding gene on chromosome 11 (5,069,572 to 5,070,497, forward strand). Ensembl gene ENSG00000273085.
Subcellular location: Cell membrane
Pathways (Reactome):
Sensory Perception: Expression and translocation of olfactory receptors
Homologues: Orthologues: dog OR52E1 (75% identical), rabbit OR52E1 (66% identical), rat Or52e51 (66% identical), tropical clawed frog or52m1 (37% identical). Paralogues in human: OR52E2 (62% identical), OR52E4 (58% identical), OR52E8 (57% identical), OR52E5 (56% identical), OR52E6 (56% identical), OR52J3 (49% identical), OR52R1 (45% identical), OR52H1 (45% identical), OR52B2 (44% identical), OR52D1 (44% identical), OR52N4 (44% identical), OR52N1 (43% identical), and 39 more.